RN7SL536P (RNA, 7SL, cytoplasmic 536, pseudogene)
Gene: Miscellaneous RNA gene on chromosome 15 (23,363,272 to 23,363,561, forward strand). Ensembl gene ENSG00000278222.
Homologues: Orthologues: pig Metazoa_SRP (54% identical), macaque Metazoa_SRP (49% identical). Paralogues in human: Metazoa_SRP (99% identical), RN7SL106P (99% identical), RN7SL238P (99% identical), RN7SL545P (99% identical), RN7SL759P (99% identical), RN7SL196P (88% identical), RN7SL286P (88% identical), RN7SL539P (88% identical), RN7SL796P (88% identical), RN7SL214P (80% identical), RN7SL736P (79% identical), RN7SL209P (78% identical), and 700 more.